INS (insulin)
Diseases named in the same sentence as INS in open-access papers (continued):
Sharing a sentence is not in itself a finding about the gene and the disease.
cancer (continued). "Lower insulin levels can diminish the proliferative and anti-apoptotic signals in cancer cells that exhibit insulin resistance, thereby potentially inhibiting cancer progression." (PMID 40040878, 2025). "Elevated insulin levels can enhance cell proliferation and inhibit apoptosis, contributing to cancer progression." (PMID 39940252, 2025). "Androgens can directly stimulate AR-positive cancer cells, while insulin and IGF promote mitotic activity in cancer cells." (PMID 40534880, 2025). "The results showed that regular exercise interventions led to a small but significant improvement in insulin levels among cancer patients." (PMID 40895542, 2025). "The findings indicate a statistically significant reduction in cancer risk when comparing GLP‐1RAs to TZD, with a RR of 0.82 [95% CI: 0.68, 0.96], and to insulin, with a RR of 0.57 [95% CI: 0.32, 0.81]." (PMID 39980820, 2025). "Disruption of copper metabolism in cancer can affect mitochondrial respiration, glycolysis, insulin signaling, and lipid metabolism." (PMID 41009634, 2025). "Analogous to what is seen in obesity (metabolic syndrome), cancer cachexia can also be described as a systemic metabolic syndrome where tumors drive the host’s hypermetabolic and insulin resistant state." (PMID 40572244, 2025). "To date, research has primarily focused on the biological functions of hsa-miR-199a-3p, particularly in the context of cancer and only a few studies related to glycemic/insulin regulation." (PMID 40904799, 2025). "Beyond metabolic regulation, insulin and insulin-like growth factors affect cancer biology by activating the HIF1 signaling pathway." (PMID 40989682, 2025). "In summary, while glucose remains the primary metabolic fuel for most somatic cells, fructose provides cancer cells with a unique metabolic advantage due to its insulin-independent entry and distinct enzymatic processing." (PMID 40520908, 2025). "For example, it would be logistically more feasible to randomize diabetic patients to receive two different types of insulin compared to randomizing cancer patients to receive two different surgical resection approaches." (PMID 39127979, 2025). "Strengths of miR-CRAFT study mainly rely within the study design that is balanced for two critical confounders of epigenetic modifications, namely cancer and insulin treatment." (PMID 40565590, 2025). "Many population studies have indicated the correlation between the level of insulin and IGF1 and the risk of certain cancers." (PMID 39940361, 2025). "Chronic high insulin levels can promote inflammation and cellular proliferation, creating an environment conducive to cancer development." (PMID 40773497, 2025). "FAs contribute to the initiation and progression of cancer via modulating immunity, inflammation, cell proliferation, apoptosis, and insulin sensitivity." (PMID 40307439, 2025). "Differential metabolites in the BV-H and MLT-L groups were collectively involved in β-alanine, histidine, vitamin digestion, and absorption, central carbon in cancer, and insulin resistance metabolic pathways." (PMID 39859456, 2025). "High blood sugar and insulin levels activate growth-promoting pathways, such as PI3K/Akt/mTOR, in colon cells, which increases the risk of cancer." (PMID 41374093, 2025). "The mechanisms connecting diabetes and cancer include increased insulin and IGF-1 signaling, which promotes cell proliferation, reduced apoptosis, and enhanced tumor growth." (PMID 40364115, 2025). "Vitamin K is a multifunctional nutrient with several functions, including bone health, cardiovascular health, insulin sensitivity, cancer prevention, immune regulation, brain health, and maternal and child health." (PMID 40718363, 2025). "There were far fewer gene expression differences observed between insulin-expressing tumour cells from the two patients (~ 600 DEGs) than between the two cancer cell populations within each patient." (PMID 40438247, 2025).
cancer (continued). "This dual suppression of IGF‐1 and insulin signaling is a key mechanism by which metformin exerts its anti‐tumorigenic effects across various cancers." (PMID 40387523, 2025). "These included insulin-expressing cancer cells, acinar cells, B cells, ductal cells, macrophages, T cells, muscle, nerve, and pancreatic stellate cells." (PMID 40438247, 2025). "Currie and associates, in 2009, analyzed the impact of monotherapy with metformin or sulfonylurea, combined therapy (metformin + sulfonylurea), or insulin in any type of cancer." (PMID 40572709, 2025). "Conducting randomized controlled trials (RCTs) that combine physical activity and nutritional strategies to improve insulin sensitivity in individuals with cancer." (PMID 38339407, 2024). "Given the established link between insulin dysregulation and poor prognosis across different cancer types, our study aimed to elucidate the effects of insulin signaling dysregulation in different tumor contexts." (PMID 38272982, 2024). "Following LCDs during cancer therapies can help manage blood sugar levels and reduce insulin resistance, thereby mitigating metabolic complications like hyperglycemia." (PMID 38893112, 2024). "Some of these extra biological pathway examples are smooth vascular muscle contraction, calcium signaling, insulin secretion, and differentiated cancer pathway." (PMID 38769480, 2024). "Potential treatments for cancer cachexia include appetite stimulants, anabolic agents, cytokine inhibitors, insulin, NSAIDs, and others." (PMID 39624846, 2024). "The following signaling pathways were shared between the upregulated and downregulated miRNA gene targets: PI3K/Akt, MAPK, Ras, Wnt, FoxO, AMPK, insulin signaling, and those involved in cancer." (PMID 39022651, 2024). "High insulin levels activate the PI3K/Akt/mTOR signaling pathway promoting cancer cell growth, survival, proliferation, metastasis, and anti-apoptosis." (PMID 39410536, 2024). "Future research should include larger populations, longer follow-up duration, insulin doses used by patients with DM, and analyze confounding factors to improve understanding of potential long-term cancer risks." (PMID 39434861, 2024). "To investigate this, we first validated the endogenous expression levels of IRS1 and IRS2 in all three types of cancer cell lines by using C-CBL targeting si-RNA (si-C-CBL) under prolonged insulin treatment." (PMID 38272982, 2024). "Conversely, the low-risk group exhibited enrichment in the following top five pathways: endocytosis, insulin signaling pathway, neurotrophin signaling pathway, pathways in cancer, and valine leucine and isoleucine degradation." (PMID 38491523, 2024). "Our research findings indicate that C-CBL mediated neddylation acts as an antagonist against insulin-associated cancer cell migration involving IRS1 and IRS2 in diverse cancer types." (PMID 38272982, 2024). "This systematic review shows that engaging in physical activity is a healthy option to combat the effects of insulin in cancer patients." (PMID 38339407, 2024). "KEGG enrichment analysis was enriched mainly in the oxytocin signaling pathway, proteoglycans in cancer, insulin signaling pathway and regulation of actin cytoskeleton." (PMID 38774751, 2024). "It has been discovered that Daf-16/FOXO-regulated genes that affect the insulin/IGF-1 pathway as influencing the formation of C. elegans cancer formation." (PMID 39558974, 2024). "In this study of patients with T2D who were cancer free at baseline, taking GLP-1RAs compared with insulin was associated with a lower risk of 10 of 13 OACs." (PMID 38967919, 2024).
cancer (continued). "The younger cohort had higher rates of both non‐insulin and insulin‐dependent diabetes, smoking, dialysis use, cancer, and chronic steroid use (p < 0.05)." (PMID 38837679, 2024). "Fasting enhances the ability of cholesterol biosynthesis inhibitors to lower cholesterol in cancer cells, and this effect is dependent on fasting-mediated reductions in insulin, IGF1, and leptin." (PMID 39595613, 2024). "In obese people, elevations in circulating leptin, insulin, and insulin-like growth factor (IGF)-1 can each contribute to the excess cancer risk." (PMID 38831236, 2024). "Several obtained results revealed that patients with a cancer diagnosis were markedly insulin resistant." (PMID 38397072, 2024). "In the plerocercoid stage, glycolysis/gluconeogenesis, proteoglycans in cancer, tight junctions, the glucagon signaling pathway, and the insulin signaling pathway were the most highly enriched KEGG pathways." (PMID 39217359, 2024). "A population-based cohort study tracking over 10,000 patients reported higher cancer-related mortality among SU and insulin users compared to those receiving metformin." (PMID 39595655, 2024). "Citrate can act as a metabolic regulator and is involved in numerous physiological and pathophysiological processes such as inflammation, cancer, insulin secretion, and neurological disorders." (PMID 38786722, 2024). "Regular physical activity, as part of a healthy lifestyle, was identified as an important strategy to improve glucose metabolism, enhance insulin sensitivity, and maintain overall glycemic control in cancer patients undergoing chemotherapy." (PMID 39088060, 2024). "Our research underscores the significant role of Cbl proto-oncogene (C-CBL) as a neddylation E3 ligase for IRS1 and IRS2, highlighting the promising potential of C-CBL as a target for regulating cancer metastasis in the context of insulin dysregulation." (PMID 38272982, 2024). "First, a surprisingly small number of studies found that analyzed insulin sensitivity in cancer patients who engaged in physical activity as an intervention to improve metabolic pathways." (PMID 38339407, 2024). "Pioglitazone, insulin, GLP-1R agonists, sulfonylureas, glargine, and DPP4 inhibitors are among the anti-diabetic drugs linked to an increased risk of cancer." (PMID 39692821, 2024). "In the case of cancer, dysregulation of insulin signaling and overexpression of transcription factor FOXC2 are related to promoting tumor proliferation and migration." (PMID 39344752, 2024). "JAK/STAT signaling is known to play an important role in metabolic regulation and growth; it has also been shown to suppress insulin signaling in contexts such as host wasting in cancer models." (PMID 38566182, 2024). "The increased expression of IR-A and an elevated IR-A: IR-B ratio facilitate the proliferative response of cancer cells to insulin and insulin-like growth factor 2 (IGF-2)." (PMID 38331804, 2024). "On the other hand, 496 DEGs were down-regulated and associated with pathways related to growth, development, and cancer, such as pathways in cancer, as well as responses to hormones, including insulin and peptide hormones." (PMID 38693536, 2024). "Preclinical data have suggested that metformin enhances PD-L1 anti-tumor effects in various cancer entities by decreasing insulin levels and inducing energetic stress." (PMID 39337118, 2024). "Glucose metabolism markers (HbA1c, HOMA-IR) and indicators of insulin secretory capacity (HOMA-beta, C-peptide) were prospectively evaluated in patients with ICI-treated cancers to determine their association with cancer prognosis." (PMID 39722806, 2024). "Insulin plays a crucial role in both normal and malignant cells, given that its receptor is commonly found in tumour cells; and insulin resistance can further promote cancer cell growth through its mitogenic and antiapoptotic activities." (PMID 39317703, 2024).
cancer (continued). "Exploring effective interventions rooted in lifestyle medicine or therapeutics with mild insulin-suppressing effects offers new possibilities for addressing conditions like obesity, chronic inflammation, and potentially certain cancers." (PMID 38339407, 2024). "Elevated levels of insulin and insulin-like growth factor-1 (IGF-1) associated with T2DM have mitogenic effects on cancer cells, promoting proliferation and inhibiting apoptosis 43,44." (PMID 39020091, 2024). "Nonetheless, dysfunction in insulin signaling has been emerging as a prominent contributor to deterioration in cancer progression." (PMID 38272982, 2024). "The insulin signaling pathway not only regulates blood glucose but also promotes neovascularization in tumors, cancer cell proliferation, and cancer progression and metastasis." (PMID 38831128, 2024). "Only four of the eleven studies assessed the impact of insulin treatment on a recurrence of the cancer." (PMID 38254789, 2024). "Preliminary results of this trial were promising; after six months of treatment, patients on metformin had significant improvements in body weight, glucose, insulin, leptin, and C-reactive protein and reduced circulating levels of the cancer antigen 15-3." (PMID 38543182, 2024). "The impact of metformin on cancer cells involves the indirect modulation of insulin-dependent pathways as well as direct effects through insulin-independent pathways." (PMID 38612893, 2024). "This review discusses the mechanisms of action involving both insulin-dependent and independent pathways, shedding light on the potential of metformin as a therapeutic agent for different types of cancer." (PMID 38612893, 2024). "Epidemiological studies found an association between high-normal levels of insulin, C-peptide, and IGF-1 with an increased risk of various cancers (such as breast, colon, and prostate)." (PMID 39434861, 2024). "LCD alters the metabolic environment that cancer cells exploit for growth and survival by reducing blood glucose levels and insulin secretion, conditions that promote the proliferation and progression of cancer cells." (PMID 38893112, 2024). "The results showed that the pathways mainly included insulin resistance, cancer pathway, PI3K-Akt signaling pathway, FOXO signaling pathway, TNF signaling pathway, and VEGF signaling pathway." (PMID 38921004, 2024). "The implications of these findings indicate the promise of directing therapeutic interventions toward the insulin/IGF-2/IR-A pathway in the context of malignant tumors." (PMID 38331804, 2024). "It is also linked to a variety of pathways that are associated with tumors, including RNA degradation, insulin signaling, metabolic pathways, cancer pathways, sphingolipid signaling, and pathways for insulin and cancer." (PMID 38572416, 2024). "MNs are now widely used in the biomedical field due to their minimal invasive, convenience, local controllable administration, and personalised design, particularly for cancer treatment, dermatological therapy, and insulin and vaccine delivery." (PMID 39554838, 2024). "Enhanced insulin sensitivity helps modulate the insulin and insulin-like growth factor-1 (IGF-1) pathways, which are implicated in the progression of several cancers." (PMID 38831183, 2024). "This systematic review presented mixed evidence on the impact of exercise interventions on insulin sensitivity in cancer patients." (PMID 38339407, 2024). "On the other hand, blood glucose and serum insulin levels are significant metabolic culprits in the extensive body of cancer studies." (PMID 39267853, 2024). "The biological pathways linking adipose tissue and cancer, involve, among others, insulin resistance, adipose-tissue derived inflammation with secretion of proinflammatory cytokines, and sex hormones metabolism." (PMID 38297030, 2024).
cancer (continued). "A study conducted by Sanaki reveals that under normal circumstances (with normal insulin levels), healthy wild-type cells eliminate cancer cells through cell competition." (PMID 38339407, 2024). "Cell culture study using different cancer cells demonstrated that insulin accelerates cancer cell growth." (PMID 39642218, 2024). "To understand the effects that ARG and insulin have on the metabolomic landscape of the cancer cells, we picked four cell lines, MDA-MB-231, A549, H1975 and KURAMOCHI, and treated them with low and high doses of ARG with/without 1 nM insulin." (PMID 38374190, 2024). "In fact, cancer cells can exhibit varying responses to insulin sensitivity and resistance depending on the type of cancer and the specific metabolic adaptation they undergo." (PMID 39410536, 2024). "Based on this, we designed Warburg therapy (i.e., using Warburg theory, glucose starvation was induced by intravenous insulin injection during cancer chemotherapy)." (PMID 39629677, 2024). "Another major protein linking mitochondrial autophagy and cancer is insulin/insulin-like growth factor (IGF)." (PMID 39763653, 2024). "In recent years, more and more studies have revealed the association between IR and the occurrence and development of cancer, with the insulin/insulin-like growth factor signaling pathway possibly playing a crucial role." (PMID 39631832, 2024). "Apart from the effect of the KD on glucose metabolism and insulin concentration, it still influences the oxidative stress of cancer cells by inhibiting ROS production and enhancing endogenous antioxidant expression in cancers in vivo." (PMID 38444674, 2024). "Apart from its multiple anti-cancer properties, it also regulates calcium and phosphate homeostasis and participates in bone mineralization, insulin secretion, and blood pressure regulation." (PMID 38671875, 2024). "Altogether, these findings suggest that neddylation genuinely participates in IRS1 and IRS2-dependent insulin signaling, effectively suppressing cancer cell migration." (PMID 38272982, 2024). "Previous study have confirmed miR-24-1-5p targets genes involved in key pathways such as the cell cycle, AMPK signaling, Hippo signaling, and insulin signaling, affecting cancer cell proliferation, metastasis and apoptosis in HCC." (PMID 38840234, 2024). "The activation of the PI3K/Akt/mTOR signalling pathway by insulin and IGFs is recognised for its role in propelling cancer progression." (PMID 39301314, 2024). "To date, most studies on the insulin analogs and cancer have had a short follow-up (less than five years)." (PMID 38254789, 2024). "High levels of insulin and IGF have been associated with risk for several obesity-related cancer types." (PMID 40443827, 2024). "Under normal conditions, insulin primarily regulates glucose metabolism with limited direct involvement in cancer progression." (PMID 39290325, 2024). "Its mechanisms of action include modulating insulin signaling, inhibiting inflammatory pathways, and inducing apoptosis in cancer cells." (PMID 39408847, 2024). "A considerable and increasing proportion of BC and RCC patients receive systemic therapies in the context of their cancer that can directly and indirectly impact glucose and insulin metabolism." (PMID 39020360, 2024). "Initial investigations have indicated that FMD can enhance insulin production, stabilize blood glucose levels, and potentially improve the efficacy of chemotherapy in patients with cancer." (PMID 39595613, 2024). "Despite the critiques, these studies were the first efforts in their analysis of the potential effects of insulin glargine on cancer development and have set the way for subsequent research." (PMID 39434861, 2024). "It is postulated that one key driver of both T2DM and cancer is insulin, a hormone that activates many pathways, which drives aggressive BC biology." (PMID 38392069, 2024).